TRPA1 (transient receptor potential cation channel subfamily A member 1)
Diseases named in the same sentence as TRPA1 in open-access papers (continued):
Sharing a sentence is not in itself a finding about the gene and the disease.
cystitis (10 papers, 2016 to 2023). Inflammation of the urinary bladder. "By contrast, in a cyclophosphamide-induced cystitis model, bladder hyperalgesia, and voiding frequency are caused by activation of TRPA1." (PMID 29249972, 2017). "RT-qPCR indicated that the mRNA level for Trpa1 was elevated in the cystitis and was decreased by SB431542 treatment." (PMID 37931000, 2023). "TRPA1 can regulate bladder pain and overactivity via the release of neuropeptides; an antagonist of TRPA1 can alleviate bladder hyperalgesia in cystitis and bladder pain." (PMID 33810314, 2021). "These TRP channels, like TRPV1, TRPV4, and TRPA1, contribute to normal voiding behavior and/or bladder hypersensitivity in experimental models of cystitis." (PMID 35008533, 2021). "The expression of TRPA1 mRNA and protein in both mucosa and DRGs is increased in cyclophosphamide-induced cystitis and can be decreased by treatment with TRPA1 antagonists." (PMID 31197115, 2019). "Further investigation is therefore required to identify the sites of TRPA1 expression responsible for the pathology of long-lasting cystitis." (PMID 29249972, 2017). "Consistently, a TRPA1 antagonist attenuates visceral nociception in an ifosfamide-induced cystitis model, although ifosfamide-induced bladder inflammation is not suppressed." (PMID 29249972, 2017). "In the present study, we investigated the pathophysiological role of TRPA1 in the H2O2-induced long-lasting cystitis mouse model." (PMID 29249972, 2017). "In the present study, we investigated the pathophysiological roles of TRPA1 in the H2O2-induced long-lasting cystitis model using TRPA1-knockout (KO) mice." (PMID 29249972, 2017). "Cystometry was performed in control and cystitis rats, following the intrathecal injection of the TRPA1 antagonists HC-030031 and A-967079." (PMID 27315798, 2016). "The antagonists prevent and reverse cystitis, suggesting that TRPA1 is pivotal for the maintenance and development of the inflammatory response and hyperalgesia." (PMID 27315798, 2016). "Accordingly, the western blotting analysis also showed the TRPA1 protein significantly increased in the DRG with cystitis(1.21 ± 0.12 vs 0.98 ± 0.08; P = 0.018)." (PMID 27315798, 2016). "The expression of TRPA1 mRNA was higher in the cystitis group in both the mucosa and DRG, but the difference was significant in the DRG (P = 0.014)." (PMID 27315798, 2016). "In this study, we aimed to investigate the effects of blocking TRPA1 via intrathecal administration of antagonists on the afferent pathways of micturition in rats with cystitis." (PMID 27315798, 2016). "The expression of TRPA1 mRNA and protein was higher in the cystitis group in both the mucosa and DRG, but the difference was significant in the DRG (P < 0.05)." (PMID 27315798, 2016). "In addition, TRPA1 antagonism reversed bladder hyperalgesia in mice with cystitis, as well as improved micturition and reversed overactive bladder-like symptoms in cystitis rats." (PMID 35077502, 2022). "In conclusion, the present study revealed that TRPA1 contributes to initial bladder hyperactivity, affecting the frequency of urination and abdominal visceral pain, but it does not appear to play a major role in the pathology of long-lasting cystitis." (PMID 29249972, 2017). "Therapeutic strategies targeting TRPA1 may be effective for minimizing bladder hyperactivity in acute cystitis, but its usefulness for chronic cystitis may be limited." (PMID 29249972, 2017). "Taken together, these results suggest that TRPA1 contributes to acute bladder hyperactivity such as frequent urination and bladder pain, but does not appear to play a major role in the pathological processes of long-lasting cystitis." (PMID 29249972, 2017). "Thus the present research was conducted to establish the animal model of acute cystitis to assess alterations in the expression and function of TRPA1." (PMID 27315798, 2016).
cystitis (continued). "The immunohistochemistry analysis showed that TRPA1 in DRG was markedly upregulated in the cystitis group (0.224 ± 0.04 vs 0.151 ± 0.02; P = 0.018) while the TRPA1 protein level in cystitis mucosa did not have any significant alteration (0.145 ± 0.02 vs 0.127 ± 0.02; P = 0.4)." (PMID 27315798, 2016). "Taken together, our results indicate that TRPA1 especially in DRG plays a key role in the occurrence of cystitis, and therefor intrathecal injection of TRPA1 antagonists might be effective in treating detrusor overactivity." (PMID 27315798, 2016). "The TRPA1 had a pronounced upregulation in DRG but more slight in mucosa in rat cystitis." (PMID 27315798, 2016). "Thus, it is likely that ROS-sensitive TRPA1 may play a key role in the pathogenesis or pathology of chronic cystitis, although this is not fully understood at present." (PMID 29249972, 2017). "TRPA1 up-regulation was reported in bladder afferents in cyclophosphamide (CYP)-induced cystitis mice, and in L6-S1 DRG of CYP-induced cystitis rats." (PMID 35077502, 2022). "After induction of cystitis by injection of cyclophosphamide, we observed a robust increase of the functional responses to agonists of TRPM3, TRPV1, and TRPA1 in bladder-innervating DRG neurons." (PMID 35008533, 2021). "Earlier work provided evidence for the role of sensory TRP channels in bladder hyperreactivity during cystitis (TRPV1 and TRPA1), the detection of noxious stimuli in the bladder (TRPA1), and cold-induced bladder reflexes (TRPM8)." (PMID 35008533, 2021). "In mice with CYP-induced cystitis, the proportion of WGA-AF555-labeled neurons responding to TRPM3, TRPV1, and TRPA1 agonists was significantly higher than in sham treated animals (p = 0.002, p < 10−6, and p = 0.02, respectively)." (PMID 35008533, 2021). "Thus, TRPA1 channels in LP-ICs may have an important role as sensors of toxic and irritant substances produced in bladder wall or pass from urine into the bladder wall if the urothelial barrier is disrupted during bladder infection or interstitial cystitis." (PMID 35069237, 2021). "Cystitis induced by intravesical H2O2 injection was histopathologically examined by HE staining of the bladder of WT and TRPA1-KO mice." (PMID 29249972, 2017). "Transient receptor potential ankyrin 1 (TRPA1), the most sensitive TRP channel to ROS, was shown to be responsible for urinary bladder abnormalities and hyperalgesia in an acute cystitis model." (PMID 29249972, 2017). "Immunohistochemistry and western blotting analysis of TRPA1 expression in DRG and mucosa of cystitis and normal group." (PMID 27315798, 2016). "Following intrathecal injection of the highly specific TRPA1 antagonists HC-030031 and A-967079,the ICI was extended, and the N-VC was suppressed in cystitis, thereby inhibiting micturition reflex hyperactivity." (PMID 27315798, 2016). "The present study demonstrates the TRPA1 was expressed in both bladder and DRG (L6-S1) and had a pronounced upregulation in DRG but more slight in mucosa in rat cystitis." (PMID 27315798, 2016). "By contrast, TRPA1 appears not to play a major role during the latter stages of long-lasting cystitis." (PMID 29249972, 2017). "It should be noted that this study has examined only the TRPA1 expression and function in the stage of acute inflammation, while a time-dependent change of TRPA1 after cystitis was not involved." (PMID 27315798, 2016). "Since H2O2 can activate TRPA1, it is conceivable that H2O2 injected intravesically could directly stimulate TRPA1 in the bladder, leading to the generation of long-lasting cystitis." (PMID 29249972, 2017). "Thus, direct stimulation of bladder TRPA1 by exogenous H2O2 appears not to play a major role in the induction of cystitis." (PMID 29249972, 2017).
cystitis (continued). "Moreover, it has been demonstrated that ROS are involved in urinary bladder disorders, and in a H2O2-induced cystitis model, TRPA1 contributed to acute bladder hyperactivity but did not seem to play a pivotal role in the pathological development of chronic cystitis." (PMID 31197115, 2019). "We also observed that the TRPA1 had much more expression in the cystitis mucosa than the normal via AGE and the fat tissue did not express TRPA1 mRNA, although they expressed GAPDH mRNA." (PMID 27315798, 2016).
Hyperglycemia (10 papers, 2013 to 2025). An increased concentration of glucose in the blood. "We next thermally activated cholinergic neurons by overexpressing TrpA1 at 29 °C and found enhanced systemic Akh response as indicated by tobi expression, as well as lipid loss and hyperglycemia, in the adult flies." (PMID 39924534, 2025). "When we administered STZ to WT and TRPA1 KO rats, we found that it induced hyperglycemia and mechanical allodynia that developed over the course of several days; both genotypes were affected to a similar degree." (PMID 31969645, 2020). "Here we confirm earlier reports that methylglyoxal (MG), one of the major dicarbonyl metabolites produced from glucose during hyperglycemia, stimulates the nociceptive ion channel TRPA1 directly through a reversible, intracellular interaction." (PMID 24167592, 2013). "Oxidative stress and increased formation of MG thus converge on the nociceptive ion channel TRPA1 during hyperglycemia, thereby selectively stimulating nociceptive fibers." (PMID 24167592, 2013). "TRPA1 can detect hyperglycemia and transmit several stimuli involved in insulin secretion." (PMID 37631083, 2023). "Studies on mouse models of T2DM have indicated that the hyperglycemia environment of T2DM prompted the increased production of reactive metabolites, such as methylglyoxal (MGO), which act as TRPA-1 agonists." (PMID 39101085, 2024). "Hyperglycemia in diabetic individuals induces accumulation of the highly reactive dicarbonyl compound methylglyoxal (MGO), which modulates TRPA1 activity." (PMID 38143915, 2023). "Knockdown of TRPA1 did not affect hyperglycemia, but it increased kidney to body weight ratio (KW/BW) and urinary albumin/creatinine ratio (ACR) levels." (PMID 38072665, 2024). "Similar results were obtained in experiments where two other TRPA1 agonists (i.e., N-methylmaleimide (i.e., NMM), an oxidizing agent that forms a covalent bond with TRPA1 and methylglyoxal (i.e., MG), a reactive molecule and an endogenous TRPA1 agonist, produced during hyperglycemia) were used." (PMID 31027359, 2019). "Hyperglycemia, at 21 days, also increased protein expression of cystathionine-β-synthase enzyme (CBS) and TRPC6, but not TRPA1 nor TRPV1, channels in dorsal root ganglia (DRG)." (PMID 30602386, 2019).
ischemic stroke (10 papers, 2018 to 2024). A stroke disorder caused by obstruction of blood flow to the brain, due to thrombotic (local blood clot formation) or embolic (due to a blood clot or other material traveling from another site) event. "In contrast, other studies showed that pharmacological activation of TRPA1 increased brain tissue loss during an ischemic stroke." (PMID 38333756, 2024). "Selective deletion of TRPA1 expression in the endothelium exacerbated the loss of brain tissue associated with ischemic stroke, providing evidence that hypoxia-induced activation of TRPA1 in the cerebral endothelium constitutes a novel adaptive response." (PMID 30239332, 2018). "Pharmacological activation of TRPA1 in vivo reduced the loss of brain tissue in response to experimentally induced ischemic stroke, whereas conditional knockout of TRPA1 in the endothelium exacerbated this damage." (PMID 30239332, 2018). "We previously demonstrated that selective knockout of transient receptor potential ankyrin 1 (TRPA1) cation channels from vascular endothelial cells exacerbated neuronal damage following ischemic stroke, and treatment with a TRPA1 agonist improved outcomes." (PMID 36793787, 2023). "In an ischemic stroke model knockout of TRPA1 in cerebral artery endothelial cells led to an increase in cerebral infarcts, whereas treatment with TRPA1 agonists reduced infarct sizes." (PMID 36768836, 2023). "Also of considerable interest are future preclinical studies investigating how pharmacological manipulation of TRPA1 channels could be used to treat inflammation, vascular dysfunction and neuronal damage associated with ischemic stroke and vascular cognitive impairment and dementia." (PMID 34064835, 2021). "Activation of vascular TRPA1 channels produces endothelium-dependent dilation of cerebral arteries and arterioles, a mechanism that is neuroprotective during ischemic stroke." (PMID 33635784, 2021). "We propose that TRPA1 activity is important in mediating hypoxia-induced dilation of the cerebral vasculature during ischemic stroke, and that this response improves collateral blood flow to the affected region to improve outcomes." (PMID 30239332, 2018). "Thus, we concluded that endothelial cell TRPA1 activity is neuroprotective following ischemic stroke." (PMID 36793787, 2023). "TRPA1 in cerebral artery endothelial cells or oligodendrocytes may play a critical role under severe hypoxic conditions (e.g., ischemic stroke)." (PMID 37478173, 2023). "Endothelial cell TRPA1 channel activity protects against ischemic strokes." (PMID 30239332, 2018).
lung adenocarcinoma (10 papers, 2017 to 2024). A carcinoma that arises from the lung and is characterized by the presence of malignant glandular epithelial cells. "In this research, TRP-related genes linked with prognosis were found in lung adenocarcinoma samples, yielding a total of 15 genes including TRPA1." (PMID 36090899, 2022). "Recent evidence suggests that the ion channel TRPA1 is implicated in lung adenocarcinoma (LUAD), where its role and mechanism of action remain unknown." (PMID 29038531, 2017). "In lung adenocarcinoma, the expression of TRPA1 and TRPV1 were upregulated by the hypoxia-inducible factor 1α (HIF1α) nuclear accumulation, finally leading to cell proliferation." (PMID 37507867, 2023). "A parallel investigation demonstrated that TRPA1 expression on the plasma membrane of human lung adenocarcinoma A549 cells can be increased by inflammatory cytokines, such as interleukin (IL)-1α, IL-1β, and tumor necrosis factor α (TNFα)." (PMID 37174661, 2023). "In agreement with this hypothesis, TRPA1 can physically associate with the fibroblast growth factor receptor 2 (FGFR2) via its NH2-terminal ARD and thereby stimulate lung adenocarcinoma (LUAD) progression and metastatic spreading in a Ca2+-independent manner." (PMID 37174661, 2023). "Lung adenocarcinoma patients with high expression levels of ISG15, MMP1, TRPA1, KRT19, and PLAU (red line) were significantly associated with poor survival rates (log rank P value: 2.3e-07, 0.00034, 0.00037, 0.00057, and 0.023, respectively) as compared to those with low expression (black line)." (PMID 35354498, 2022). "In addition, in lung adenocarcinoma, direct binding of TRPA1 to FGFR2 resulted in a constitutive receptor activation, thereby promoting tumor progression." (PMID 34440820, 2021). "Experiments performed on lung adenocarcinoma cells proposed a bold hypothesis: the N-terminal ankyrin repeats of TRPA1 directly bind to the C-terminal proline-rich motif of the fibroblast growth factor receptor 2 (FGFR2), inducing the activation of the receptor through the MAP kinase pathway." (PMID 37507867, 2023). "The results showed that compared to BEAS-2B cells, KRT80, TRPA1, and C1QTNF6 were highly expressed in two lung adenocarcinoma cell lines (A549 and NCI-H1299)." (PMID 39247607, 2024). "Our results are consistent with previous findings obtained in lung adenocarcinoma and suggest that cell invasion in this context involves a crosstalk between FGFR2 and TRPA1, which implies a pore-independent function of the channel." (PMID 38339360, 2024). "To estimate the survival function of ISG15, MMP1, TRPA1, KRT19, and PLAU, we performed KM plotter analysis generated for groups of lung adenocarcinoma patients based on their expression levels." (PMID 35354498, 2022). "TRPA1 and FGFR2 binding events are carcinogenic drivers in lung adenocarcinoma." (PMID 36090899, 2022).
myocardial infarction (10 papers, 2019 to 2024). Gross necrosis of the myocardium, as a result of interruption of the blood supply to the area, as in coronary thrombosis. "The researchers suggested that the opioid-caused decrease in myocardial infarct size was mediated by TRPA1 as its pharmacological inhibition prevented morphine’s ability to reduce infarction size." (PMID 38333756, 2024). "This is beneficial for the pharmacological use of TRPA1 antagonists, as a risk of cardiovascular side effects in the case of myocardial infarction appears unlikely." (PMID 36768836, 2023). "Transient receptor potential cation channel subfamily A member 1 (TRPA1), an ion channel primarily expressed on sensory neurons, can be activated by substances occurring during myocardial infarction." (PMID 36768836, 2023). "The study evaluated the effects of treatment with a TRPA1 agonist and antagonist in experimental acute myocardial infarction." (PMID 36768836, 2023). "In the context of myocardial infarction, rats received a TRPA1 agonist, an antagonist, or vehicle at different time points, and infarct size was assessed." (PMID 36768836, 2023). "In CFs from TRPA1-deficient mice the transdifferentiation evoked by TGF-β is strongly reduced; in vivo, cardiac fibrosis is reduced in TRPA1-KO mice after myocardial infarction but is increased in WT mice treated with the TRPA1 agonist cinnamaldehyde." (PMID 32013125, 2020). "Moreover, most studies are about TRPA1’s role in cerebral, peripheral vascular, and myocardial infarctions." (PMID 38333756, 2024). "However, when this study was conceived in 2018, the available evidence regarding the role of TRPA1 in myocardial infarction was limited." (PMID 36768836, 2023). "However, another study revealed that the genetic ablation of TRPA1 significantly decreased myocardial infarction after IR in mice." (PMID 33810314, 2021). "Thus, TRPA1 appears to be involved in the regulation of cardiac function including fibroblasts under various conditions (myocardial infarction, heart failure, etc.)." (PMID 33458442, 2021). "Furthermore, based on a recent study, TRPA1 inhibitors might have beneficial effects when given long-term after myocardial infarction by improving myocardial function, reducing fibrosis, and promoting angiogenesis." (PMID 36768836, 2023). "Finally, acidosis activated human TRPA1 in pathologies such as myocardial infarction or peripheral vascular occlusive disease, but it still has to be proven that targeting TRPA1 could alleviate acidosis evoked-pain in clinical trials." (PMID 31197115, 2019). "With respect to pharmacological activation, channel desensitisation of myocardial TRPA1 might have been helpful, hence the application of JT010 well before the myocardial infarction (time point ‘Pre’)." (PMID 36768836, 2023). "TRPA1 does not seem to play a major role in the cell damage inflicted by acute myocardial infarction." (PMID 36768836, 2023). "In the context of a myocardial infarction model, neither TRPA1 activation or inhibition at different time points in rats, nor the absence of TRPA1 in mice conferred relevant protective effects in this study." (PMID 36768836, 2023). "However, unlike the other TRPA1 activators, cinnamaldehyde did not impact myocardial infarct size." (PMID 38333756, 2024).